TXNIP (thioredoxin interacting protein)
Diseases named in the same sentence as TXNIP in open-access papers (continued):
Sharing a sentence is not in itself a finding about the gene and the disease.
diabetes (continued). "Due to the significant role of TXNIP in diabetes-related pathologies and on the possible interactions of diabetes and/or insulin resistance in AD pathologies, further studies using brain tissues from cases with and without history of diabetes or insulin resistance would be informative." (PMID 39483368, 2022). "As reviewed elsewhere, glucose-induced higher tissue TXNIP expression has become a relevant therapeutic target not only to improve insulin secretion and sensitivity, but also for ameliorating the long-term microvascular and macrovascular complications of diabetes." (PMID 33567593, 2021). "In addition to TXNIP and the Trx/TrxR redox system, other ROS generating systems (NADPH oxidase and Xanthene oxidase) and anti-oxidants (GSH, SOD1, and SOD2) may also be involved in dysregulation of the mitochondrial–lysosomal axis in diabetes and under glucolipotoxicity." (PMID 34940029, 2021). "Therefore, the present study aims at elucidating how RPTCs respond to diabetes-induced ROS accumulation under the condition of FOXO1 overexpression, contributing to interstitial fibrosis and apoptosis, and at determining whether the effects occur downstream of the TXNIP-TRX." (PMID 30962862, 2019).
Hyperglycemia (119 papers, 2007 to 2026). An increased concentration of glucose in the blood. "TXNIP hypomethylation in blood cells was found to be associated with hyperglycemia in individuals from Taiwan, France, the USA and China." (PMID 38755631, 2024). "A recent meta-analysis of epigenome-wide association studies showed that maternal hyperglycemia during pregnancy is associated with reduced offspring DNA methylation at two CpG sites located in the thioredoxin interacting protein (TXNIP) gene." (PMID 37239377, 2023). "Prolonged hyperglycemia causes upregulation of TXNIP, a modulator of NLRP3, which in turn will activate inflammatory signaling pathways." (PMID 37762961, 2023). "TxNIP is induced in response to cellular stress, and it is associated to hyperglycemia and other stress diseases." (PMID 37298303, 2023). "During the activation signal, oxidative stress generated by hyperglycemia causes TXNIP and thioredoxin (Trx) to dissociate." (PMID 35692570, 2022). "NRF2 regulates the transcription of other genes whose physiological expression is altered by hyperglycemia and oxidative stress, such as the gene encoding thioredoxin interacting protein (TXNIP)." (PMID 35883908, 2022). "TXNIP expression has been strongly linked to hyperglycemia in retinal cell cultures, and its sustained expression over time leads to oxidative stress, inflammation, and premature cell death." (PMID 35883908, 2022). "There was also evidence of persistent hypomethylation of the thioredoxin-interacting protein (TXNIP) gene associated with hyperglycemia and related complications." (PMID 35004678, 2021). "TXNIP is a glucose sensor whose expression has been strongly associated with both hyperglycemia and diabetic complications." (PMID 33164750, 2020). "TXNIP expression is maintained as long as hyperglycemia exists and causes cellular oxidative stress, inflammation and pre-mature cell death." (PMID 33302369, 2020). "Hyperglycemia is also associated with increased expression of TXNIP via the glucose-response element in its gene." (PMID 32508651, 2020). "TXNIP localizes both in the cytosol and mitochondrion, therefore, its overexpression under chronic hyperglycemia causes cellular oxidative stress and premature cell death, including beta cells." (PMID 31355358, 2018). "After 3 months of mild hyperglycemia, GK islets show an upregulation of the gene encoding thioredoxin-interacting protein, which is induced by hyperglycemia and inhibits thioredoxin antioxidant function." (PMID 19742300, 2009). "Our data demonstrate that hyperglycemia-induced TXNIP elevation is associated with decreased TRX activity resulting in increasing levels of ROS in MDA-MB-231 cells." (PMID 17555594, 2007). "Our study opens new avenues for the investigation of the consequences of the described hyperglycemia-TXNIP-TRX-ROS axis on susceptibility to oxidative stress in oncogenesis and tumor progression." (PMID 17555594, 2007). "A recent study has demonstrated that hyperglycemia-induced increased level of TXNIP is associated with activation of p38 MAP kinase in human ASMCs." (PMID 17555594, 2007). "A recent study has also shown that hyperglycemia causes oxidative stress through inhibition of TRX function by TXNIP in human aortic smooth muscle cells." (PMID 17555594, 2007). "For instance, TXNIP, which includes cg19693031 (chosen in 43 DNAm-metabolomics models), was previously associated to hyperglycaemia and insulin resistance, and ABCG1, nearby cg06500161 (in 42 DNAm-metabolomics models) was associated to plasma lipid levels and stroke." (PMID 39154540, 2024). "Finally, increased Mondo A/Mlx signaling in beta-cells in persistent hyperglycemia is linked to increase in TXNIP, inflammation, impaired insulin secretion, and apoptosis." (PMID 38292764, 2023).
Hyperglycemia (continued). "We hypothesize that endothelial-specific thioredoxin-interacting protein knock-out (EC-TXNIP KO) mice will be more resistant to the neurovascular damage (hemorrhagic-transformation-HT) associated with hyperglycemia (HG) in embolic stroke." (PMID 34681207, 2021). "More recent mechanistic studies suggest that TXNIP may play a causal role in β-cell damage and death in response to hyperglycemia, as TXNIP overexpression causes β-cell apoptosis, and TXNIP deficiency promotes β-cell survival." (PMID 34557160, 2021). "Therefore, TXNIP causes cellular oxidative/nitrosative stress, organelle damage, and premature cell death under hyperglycemia and DR." (PMID 33302369, 2020). "The TXNIP promoter linked gene expression may also have certain advantages in application in other diseases in that such a construct will be activated by hyperglycemia encountered after each meal, which may be considered its physiological inducer." (PMID 31355358, 2018). "TXNIP deficiency rescued the extreme hyperglycemia‐induced death observed in Akita mice." (PMID 30168649, 2018). "Studies have demonstrated decreased skeletal muscle and blood TXNIP DNA methylation and increased skeletal muscle TXNIP expression in subjects both at increased risk of as well as overt T2DM, and hyperglycemia increases TXNIP expression in various cells and tissues." (PMID 29077742, 2017). "Indeed, common differentially methylated loci were found, including changes in thioredoxin-interacting protein (TXNIP) known to be associated with hyperglycemia." (PMID 27469259, 2016). "Moreover, TXNIP deficiency was shown to prevent beta-cell apoptosis and hyperglycemia in rodent models of type 2 diabetes." (PMID 22194917, 2011). "Thioredoxin-interacting protein (Txnip, 4.4-fold upregulated) has been implicated in the pathogenesis of diabetic nephropathy, and may mediate the ROS-dependent adverse effects of hyperglycemia on mesangial cells in vitro." (PMID 24827579, 2014). "Prior research has demonstrated that hyperglycemia-induced overexpression of TXNIP can lead to pancreatic β-cell apoptosis, cardiomyopathy, and metabolic disorders." (PMID 39827095, 2025). "Upstream, TXNIP links hyperglycemia to oxidative stress and mTOR/EMT activation; knockdown reduces ROS and renal injury and associates with mTOR activity in human biopsies." (PMID 41009556, 2025). "Hyperglycemia-induced ROS generation increases the level of thioredoxin-interacting protein (TXNIP), which directly binds with NLRP-3 and activates it." (PMID 39501954, 2025). "Under diabetogenic β-cell stresses, such as hyperglycemia, the endogenous thioredoxin inhibitor, thioredoxin interacting protein (TXNIP), is upregulated." (PMID 40136648, 2025). "Another study on hyperglycemia-treated C17.2 neural stem cells has shown decreased expression levels of miR-17-5p, leading to upregulation of its target gene, TXNIP." (PMID 40559375, 2025). "TXNIP is highly upregulated in response to hyperglycemia in models of β cell dysfunction, including chronic culture in OPG and β cell Clec16a-KO mice." (PMID 38935435, 2024). "TXNIP mediates hyperglycemia-induced oxidative stress while stimulating the NOD-like receptor protein (NLRP3) inflammasome assembly, leading to inflammatory responses in the immune cells." (PMID 37124219, 2023). "Under hyperglycemia, thioredoxin-interacting protein (TXNIP) expression is enhanced in ARPE-19 cells." (PMID 37334304, 2023). "Intracellular high glucose concentrations induce TXNIP, which is known to mediate hyperglycemia-induced oxidative stress and to deter glucose availability to the neural cells in the brain." (PMID 37124219, 2023). "Hyperglycemia increases Thioredoxin-interacting protein (TXNIP) levels and elevated TXNIP levels are markers of glucotoxicity effects including reduced skeletal muscle and cardiac glucose uptake, diabetic cardiomyopathy, and impaired β-cell function." (PMID 37626210, 2023).
Hyperglycemia (continued). "Our study demonstrates that the modulation of Glo-1 underlying dicarbonyl stress leading to hyperglycemia preceding vascular complications correlates with the expression of VCAM and TXNIP in micro- and macrovessels." (PMID 37759966, 2023). "The TXNIP protein, which is sensitive to intracellular glucose levels, is activated during hyperglycemia and under conditions of oxidative stress that are exacerbated by tPA." (PMID 37511788, 2023). "It has been proposed that under normal conditions, endothelial cells contain a significant level of Trx activity due to the downregulation of TxNIP, but hyperglycemia-induced vascular dysfunction induces that protein." (PMID 37298303, 2023). "This is an indication that Glo-1, VCAM and TXNIP are upregulated in hyperglycemia leading to oxidative stress, and mediate endothelial dysfunction, eventually causing vascular complications in T2DM." (PMID 37759966, 2023). "TXNIP upregulation was gradually amplified with increasing glucose concentration up to 20 mM (p < 0.05), reflecting clinically relevant severe hyperglycemia." (PMID 37124219, 2023). "Thioredoxin-interacting protein (Txnip), a cellular oxidative stress regulator, is activated by hyperglycemia and limits glucose absorption into fat and muscle tissues." (PMID 36077011, 2022). "Persistent hyperglycemia in pancreatic islets induces ROS accumulation, leading to elevated thioredoxin-interacting protein (TXNIP), activation of the NLRP3 inflammasome, and induction of caspase-1-dependent IL-1β maturation." (PMID 35844498, 2022). "Streptozotocin (STZ)-induced hyperglycemia directly stimulates TXNIP expression through increased intracellular calcium ion (Ca2+) levels in the retina." (PMID 36017183, 2022). "Substantial evidence suggests that hyperglycemia promotes the expression of TXNIP through multiple pathways." (PMID 36017183, 2022). "Another study found that SNHG15 inhibited hyperglycemia-induced endothelial dysfunction by enhancing the ubiquitination of thioredoxin-interacting protein." (PMID 34980176, 2022). "The expression of TXNIP is induced by a number of cellular stress mechanisms, but most widely studied has been hyperglycemia and endoplasmic reticulum stress." (PMID 39483368, 2022). "This study is the first to extensively examine the genetic and hyperglycemia contextual effects on cg19693031 methylation, laying the groundwork for a better understanding of TXNIP’s pleiotropic pathophysiological effects in the development of disease." (PMID 35456489, 2022). "Hyperglycemia also induces the expression of TXNIP (thioredoxin-interacting protein), which activates NADPH oxidases to produce reactive oxygen species." (PMID 35126159, 2022). "Under sustained hyperglycemia, TXNIP migrates to the mitochondrion and inhibits the Trx2/TrxR2 anti-oxidant system." (PMID 34940029, 2021). "TXNIP was upregulated by hyperglycemia in the midbrain, accompanied by autophagy inhibition, and dopaminergic (DA) neuron loss." (PMID 34162834, 2021). "Hyperglycemia can also induce overexpression of thioredoxin-interacting protein (TXNIP), which plays a critical role in the TXNIP-dependent NLRP3 inflammasome activation." (PMID 34631209, 2021). "Study showed that Exendin-4, a GLP analog, protected against hyperglycemia-induced cardiomyocyte pyroptosis via the AMPK/thioredoxin-interacting protein (TXNIP) pathway." (PMID 35096293, 2021). "TXNIP expression remains elevated as long as hyperglycemia persists, while insulin and insulin-like growth factor 1 (IGF-1) reduce TXNIP expression, however, it lasts for a few hours only if hyperglycemia persists." (PMID 34940029, 2021). "Hyperglycemia in vivo and high glucose conditions (HG) in vitro promote TXNIP expression, TXNIP plays a pathological role in both type 1 and Type 2 diabetes and is also involved in the pathophysiology of diabetic complications, including diabetic retinopathy." (PMID 34827650, 2021).
Hyperglycemia (continued). "Prolonged hyperglycemia in pancreatic islets induces ROS accumulation, which results in elevation in TXNIP to activate NLRP3 inflammasome activation and to induce caspase-1-dependent IL-1β maturation." (PMID 34631209, 2021). "Recent studies have shown that hyperglycemia increases the production of ROS in myocardial cells, which in turn upregulates NF-κB and TXNIP." (PMID 34093185, 2021). "Thioredoxin interacting protein (TXNIP) mediates hyperglycemia-induced oxidative damage and inflammation in the brain, while reducing cerebral glucose uptake/utilization." (PMID 34054705, 2021). "Tissue plasminogen activator (tPA)–induced cerebrovascular damage is related to the upregulation of thioredoxin-interacting protein (TXNIP), and upregulation of thioredoxin-interacting protein (TXNIP) has harmful effects on hyperglycemia." (PMID 35008558, 2021). "Using a rat insulinoma cell line INS-1E to represent pancreatic beta cells, it was shown that hyperglycemia activated TXNIP expression and inhibited the activation of AMPK." (PMID 33302545, 2020). "Hyperglycemia-induced expression of TXNIP is observed in the vasculature, pericytes, and the RPE, suggesting a conserved mechanism across cell types." (PMID 32977483, 2020). "Third, hyperglycemia activates the thioredoxin-interacting protein (TXNIP)-mediated NLRP3 inflammasome in adipose tissues and microvascular endothelial cells, which are relevant to type 2 diabetes and myocardial ischemic/reperfusion injury, respectively." (PMID 30717382, 2019). "TXNIP is induced strongly by high glucose and its metabolites with minutes and remains elevated as long as hyperglycemia persists." (PMID 31355358, 2018). "Akita mice showed severe and progressive hyperglycemia with time after 4 weeks of age; however, TXNIP‐/‐/Akita (KO/Akita) mice had significantly lower glucose levels than Akita mice at all the time points." (PMID 30168649, 2018). "After 36 h exposure to hyperglycemia, phosphorylated Akt, nuclear Nrf2, and HO-1 expression levels were significantly decreased, whereas TXNIP expression level was remarkably increased compared with the control group (P< 0.01)." (PMID 29507694, 2018). "On the other hand, hyperglycemia-induced TXNIP overexpression is defined as a poor prognostic marker in pancreatic cancer." (PMID 30627326, 2018). "Previous studies have found that sustained hyperglycemia triggers the production of ROS, which directly or by stimulating the release of thioredoxin interacting protein (TXNIP) indirectly activate NLRP3 inflammasome formation." (PMID 28182085, 2017). "Hyperglycemia upregulates thioredoxin interacting protein (TXNIP) expression, which in turn induces ROS production, inflammatory and fibrotic responses in the diabetic kidney." (PMID 27381856, 2016). "Thioredoxin-interacting protein (TXNIP) as a natural inhibitor of thioredoxin is an early-response gene which is markedly induced by hyperglycemia." (PMID 27381856, 2016). "Collectively, hyperglycemia-induced TXNIP contributes to the dysregulation of tubular autophagy and mitophagy in diabetic nephropathy through activation of the mTOR signaling pathway." (PMID 27381856, 2016). "An important molecular switch that translates the presence of hyperglycaemia into proinflammatory conditions is the thioredoxin-interacting protein (TXNIP)." (PMID 26940592, 2016). "Our results suggest that TXNIP is an early response gene that is highly induced by hyperglycemia and diabetic nephropathy." (PMID 26881256, 2016). "In summary, our study demonstrated that under hyperglycemia TXNIP-driven NADPH oxidase (gp91phox) upregulation is accounted for NALP3 inflammasome activation ensuing podocytes injury." (PMID 25834832, 2015). "TXNIP has been recently shown to be a key mediator in hyperglycemia-mediated inflammatory response and beta-cell apoptosis." (PMID 25193495, 2014).